PTPN11 (protein tyrosine phosphatase non-receptor type 11)
Diseases named in the same sentence as PTPN11 in open-access papers (continued):
Sharing a sentence is not in itself a finding about the gene and the disease.
RASopathies (94 papers, 2012 to 2026). "The most frequently mutated RASopathy gene is PTPN11, which encodes the tyrosine phosphatase SHP2 that is thought to act upstream of RAS." (PMID 41248180, 2025). "Variants in PTPN11 are responsible for RASopathies, including NS and NSML, with a prevalence of up to 50%." (PMID 38674380, 2024). "Recent work revealed presynaptic impairments upon expression of RASopathy-linked PTPN11 variants in Drosophila." (PMID 39570442, 2024). "The aim of this study was to learn about the molecular base of a large cohort of patients with RASopathies, with particular emphasis on patients with pathogenic variants in genes other than PTPN11, and its potential impact on rGH treatment indication." (PMID 37568403, 2023). "NS is the most common type of RASopathy, and is a rare genetically heterogeneous autosomal dominant disorder caused by mutations in either the PTPN11, SOS 1, KRAS, BRAF or RAF1 genes." (PMID 37106005, 2023). "It is generally observed that the spectrum of mutations in the Rasopathies and in cancer minimally overlap, as exemplified by PTPN11 and BRAF56,57." (PMID 35768438, 2022). "It is noteworthy that the short term effect on patients with PTPN11 mutations is less prominent than on patients with other RASopathies-associated mutations." (PMID 36407105, 2022). "We then performed target deep sequencing with the RASopathy panel which revealed the pathogenic variant c.1520 C>A; p.(Thr507Lys) in PTPN11 (NM_002834.3) with a variant allele frequency (VAF) of 12%." (PMID 35778969, 2022). "MEK inhibition also reversed RASopathy phenotypes in PTPN11- and NRAS-associated zebrafish models of NS, BRAF- and MAP2K1-associated zebrafish models of CFC, and ARAF-associated zebrafish models of CCLA." (PMID 35178568, 2022). "NS (MIM #163950) is the most common of the RASopathies and PTPN11 is the most frequently mutated among the genes of the RAS/MAPK signal cascade." (PMID 35778969, 2022). "In conclusion we report the first case of a mosaic RASopathy caused by a pathogenic variant in PTPN11, consistent with an overgrowth‐vascular malformation with cancer predisposition." (PMID 35778969, 2022). "Regarding diagnosis of other RASopathies patients with multiple lentigines, genetic tests were needed to exclude candidate RASopathy genes, such as PTPN11 and RAF1, mutations." (PMID 32357851, 2020). "Rapidly progressive HCM, resulting in an early death, is uncommon in RASopathy patients except those with specific mutations in exon 13 of the PTPN11 gene." (PMID 30732632, 2019). "Altered glial number and function are observed in response to RASopathy-linked Nf1, Ptpn11/Shp2, and Ras mutations." (PMID 31017896, 2019). "We also found that rapidly progressive HCM was uncommon in RASopathy patients, except those with specific mutations in exon 13 of the PTPN11 gene." (PMID 30732632, 2019). "In subjects with a clinical suspicion of a RASopathy or neurocutaneous disorder, the mutation detection rate was 72.2% (26/36), with variants distributed in ten different genes, mainly PTPN11 (22.2%), and with only one causative variant in NF1 (2.7%)." (PMID 31370276, 2019). "Searching for co‐occurring mutated genes revealed the RASopathy genes PTPN11 and RASA2, as well as another RAS domain‐containing gene RASSF2 enriched in the NF1 subtype after adjustment for mutational burden." (PMID 28267273, 2017). "Additionally, RASopathy PVs, mostly linked to the PTPN11, were observed at a frequency of 5.7% based on pooled data." (PMID 40289159, 2025). "Additionally, co-occurring PVs in other RASopathies-associated genes were noted in eight cases, including seven with PTPN11 PVs and one with a KRAS PV." (PMID 40289159, 2025). "For example, mutations to PTPN11 can lead to different RASopathies through gain of function." (PMID 38521964, 2024). "Finally, we also quantified abundance of synaptic vesicle-associated protein Syn1/2, which was shown to be regulated in synapses of flies expressing RASopathy-linked PTPN11 variants." (PMID 39570442, 2024).
RASopathies (continued). "Indeed, pathogenic variants in PTPN11 cause greater than 50% of all cases of NS, a finding that paved the way for our understanding of RASopathies." (PMID 35266292, 2022). "Given that JMML is a major cause of death in PTPN11-associated NS patients the possibility to treat PTPN11 mutation associated RASopathies with SHP2 inhibitors also needs to be explored, although clinically suitable inhibitors which bind to active SHP2 would be required." (PMID 36755664, 2022). "In fact, growth retardation appears to be significantly less severe and less frequent in patients with NSML and NS associated with SOS1 mutations compared to patients with NSSD associated with pathogenic variants in other RASopathy genes, such as patients with PTPN11, RAF1, and KRAS mutations." (PMID 36060964, 2022). "Expressing PTPN11 disease isoforms primarily drove ectopic wing cross-veins, suggesting a more cell type-specific effect of this class of RASopathy variants as has been reported in murine RASopathy models." (PMID 33855281, 2021). "However, rapidly progressive HCM, resulting in an early death, was uncommon in RASopathy patients except those with specific mutations in exon 13 of the PTPN11 gene." (PMID 30732632, 2019). "In addition, it has been confirmed by molecular diagnosis that AVCD is a part of the phenotypic spectrum of CHDs found in patients with RASopathies, in particular those caused by PTPN11 and RAF1 gene mutations, as the third most common CHD." (PMID 27990414, 2016). "As the RASopathy model, we used mice heterozygous for the floxed mutation Ptpn11D61Y or KrasV14l as well as for the Emx1-cre allele and as the control, their littermates homozygous for the Ptpn11 or Kras wild-type allele and heterozygous for the Emx1-cre allele." (PMID 38910965, 2024). "More than 90% of JMML cases harbor germline or somatic mutations in one of five canonical driver genes-PTPN11, NRAS, KRAS, NF1, or CBL-establishing JMML as the prototypical malignant manifestation of RASopathy biology." (PMID 42193013, 2026). "Src homology 2 (SH2) domain-containing phosphatase-2 (SHP2, PTPN11) is implicated in diseases such as cancer and RASopathies, where it is often mutated." (PMID 41510638, 2026). "More than 38% cases (12 cases) had variants in PTPN11, 5 had variants in SOS1 and RAF1 each, making these three the most common genes leading to RASopathy disorders." (PMID 41292581, 2025). "Upstream RASopathy variants in the NF1, SHP2 (encoded by Ptpn11) and RAS proteins have been shown to modulate PI3K/Akt, PKC and/or Rho/ROCK activity, in addition to the ERK1/2 pathway." (PMID 38826084, 2024). "Genes associated with the Ras/MAPK pathway, including PTPN11, KRAS, NRAS, SOS1, SHOC2, and SHP2, are examples of mutations linked to the clinical presentation of “RASopathies” and are inherited in an autosomal dominant manner." (PMID 37504294, 2023). "We have previously used this approach to target the RASopathy gene Ptpn11 in the early oligodendrocyte lineage." (PMID 37684687, 2023). "Further, we provide evidence that multiple PTPN11 RASopathy lines regulate the JNK pathway in a distinct manner." (PMID 33855281, 2021). "Among these are three RASopathy genes (RAF1, RIT1 and PTPN11), which have been shown to cause isolated LVH in some patients, but have only been comprehensively evaluated in a small number of studies." (PMID 33673806, 2021). "Seven of eight patients were characterized by NGS, and in all of them mutations of RASopathy genes were detected (NRAS 4, KRAS 1, CBL 1, PTPN11 1)." (PMID 32344757, 2020). "In the current study, we present the mutation spectrum and clinical outcome of 47 unrelated children with RASopathy and HCM, which demonstrated that NSML-associated PTPN11 mutation was the most common cause of RASopathy-associated HCM." (PMID 30732632, 2019). "Examples of genes associated with these so-called “RASopathies” include PTPN11, KRAS, NRAS, SOS1, SHOC2, and SHP2, among others." (PMID 29922296, 2018).
RASopathies (continued). "Herein, we confirmed that mutations in the RASopathy genes RASA2 and PTPN11 were enriched in the NF1 subtype and also identified RASSF2, a RAS domain‐containing gene, as enriched in the NF1 subtype." (PMID 28267273, 2017). "Some of these genes increase predisposition to cancer, for example, in rasopathies, and BRAF, KRAS, HRAS, NF1, NRAS PTPN11, RAF129." (PMID 27080396, 2016). "The RASopathies, collectively, are a spectrum of genetic syndromes caused by mutations in genes involved in the RAS/ mitogen-activated protein kinase (MAPK) pathway, including but not limited to PTPN11, NRAS, KRAS, HRAS, BRAF, and MAP2K1." (PMID 39385823, 2024). "Estimations of Sanger sequencing prices were performed for five genes most commonly associated with RASopathies (BRAF, NF1, PTPN11, RAF1, and SOS1), and three genes, TCOF1, CHD7, and NIBPL most commonly associated with Treacher Collins, CHARGE, and Cornelia de Lange syndromes, respectively." (PMID 37815686, 2024). "Notably, the ESTAND patients with PTPN11 p.N308D and p.M504V had all major RASopathy-linked clinical conditions, and the GEMINI case carrying PTPN11 p.N58D had been suspected with NS during his medical assessment." (PMID 38654924, 2024). "Those RASopathy genes with ubiquitous or enriched GABAergic expression compared with excitatory cells, including Hras, Kras, Mapk1, Ptpn11, Sos1 and Spred1, may be of particular relevance." (PMID 37254876, 2023). "Importantly, the discovery of PTPN11 in NS paved the way to the discovery of the other RASopathy genes in the pathway and to the birth of “RASopathies” as a field of research and investigation." (PMID 35266292, 2022). "These drugs, which include RMC-4630, have not yet been tested in RASopathy models, but are promising potential therapeutics for all RASopathies with aberrant MAPK activity except for PTPN11-associated NS, because these inhibitors have decreased binding affinity for variant PTPN11." (PMID 35178568, 2022). "As expected, RAS proteins are the ones with the highest number of associations, although RASopathies related to SPRED1, MEK1/2, PTPN11, FGFR3 and SPRY1 may regulate RAS signaling differently, affecting primarily the classical RAS versus RRAS signaling." (PMID 34229750, 2021). "In contrast to RASopathy-linked PTPN11 or RAS mutants, we found little evidence that Raf1L613V expression significantly alters global cortical excitatory or PV-expressing inhibitory neuron number." (PMID 31017896, 2019). "RASopathy-associated HCM is a heterogeneous genetic condition characterized by early-onset cardiac hypertrophy and a high prevalence of co-existing congenital heart disease, which is most frequently related to specific mutations in the PTPN11 gene." (PMID 30732632, 2019). "RASopathy-associated HCM is a genetically heterogeneous condition involving diverse genes within the RAS-MAPK pathway, but frequently related to NSML-associated PTPN11 mutations." (PMID 30732632, 2019). "We included 63 Chinese patients with RASopathies that had previously tested negative for PTPN11 and HRAS mutations." (PMID 29402968, 2018). "In addition, all 26 NF1 mutant BRAF-RAS wild-type melanomas carried mutations in other known RASopathy genes, including RASA2, PTPN11, SOS1, RAF1 and SPRED1." (PMID 28637487, 2017). "Furthermore, it also enabled us to determine if there were differences in phenotype- or treatment efficacy compared to other mouse models of RASopathies caused by mutations in up-stream regulators of HRAS protein, such as NF1, SHP2/PTPN11, and SPRED1." (PMID 28455524, 2017). "Since RASopathies are neurodevelopmental disorders and since there is evidence that Ptpn11 is required for neuronal outgrowth, we tested whether the expression of Ptpn11D61Y affects neuronal morphology and synaptogenesis." (PMID 28346493, 2017).
RASopathies (continued). "Moreover, while in Drosophila the synaptic abundance of phosphoprotein Syn was elevated in NMJ synaptic boutons in animals expressing RASopathy-linked PTPN11 variants, we did not observe any changes." (PMID 39570442, 2024). "Thus, the expression of RASopathy-related PTPN11 variants affects neuronal transmission not only directly through changes in the intracellular signalling but also indirectly inducing maladaptive functional changes in neuronal networks." (PMID 39570442, 2024). "Here, we report the first case of a mosaic RASopathy caused by a pathogenic variant in PTPN11, with a phenotype consistent with overgrowth and vascular proliferation associated with cancer predisposition and lacking any of the key features observed in the germline RASopathies." (PMID 35778969, 2022). "This also precluded assessment of burden for CR genes that operate by gain-of-function mechanisms in cancer, such as protein tyrosine phosphatase non-receptor type 11 (PTPN11) and other RASopathy genes." (PMID 33084842, 2021). "Phosphorylation of the RASopathy proteins RAF1, PTPN11, and BRAF is altered in NS and NSML due to mutations in their corresponding genes, whereas RASA1 altered phosphorylation is associated to mutant SHP2 models and not to its own mutation." (PMID 34229750, 2021). "Our reported proportion may be an underestimate of the true prevalence of RASopathy findings, as earlier versions of the HCM and cardiomyopathy panels utilized in this study did not include the most common of the RASopathy genes associated with left ventricular hypertrophy (PTPN11, RAF1, RIT1)." (PMID 33673806, 2021). "BRAF, CBL, NF1, PTPN11, RAF1, SOS1 and SOS2 contain at least 20 phosphosites each, and they account for 326 of the phosphosites identified in RASopathy proteins (61% of the total)." (PMID 34229750, 2021). "Expressing human RASopathy isoforms of KRAS, HRAS, RAF1, BRAF, and PTPN11 in Drosophila, we report important differences between disease isoforms including distinct signaling pathways and drug responses." (PMID 33855281, 2021). "Because of their functional significance RAS signaling pathway components including NRAS, KRAS, NF-1, PTPN11, and CBL were summarized as RASopathy genes within one category." (PMID 32344757, 2020). "The mean (±SD) number of genes per panel was 33±25, including 8±0.3 sarcomere genes, 4±2 storage cardiomyopathy, and RASopathy genes (LAMP2, PRKAG2, TTR, GLA, PTPN11, RIT1, and RAF1) and 22±23 other genes (range, 0–75)." (PMID 30681346, 2019). "As one of the most commonly mutated genes in RASopathies, PTPN11 encodes SHP2, a non-receptor tyrosine phosphatase, which plays positive regulatory roles in signal transduction, particularly in the RAS pathway." (PMID 34445638, 2021). "The 256 patients who were found to be PTPN11 variant-negative are the subject of an NGS panel study involving 22 other genes implicated in causation of NS and other RASopathies." (PMID 32164556, 2020). "But, whilst mutant NF1 is known to cooperate with RASopathy genes (RASA2, PTPN11, SOS1, RAF1 and SPRED1) in melanoma and although NF1 is found to be frequently mutated (25–30%) in melanomas harbouring wild-type BRAF and NRAS, it is curious that melanoma is not a tumour type associated with NF1." (PMID 28637487, 2017).
LEOPARD syndrome (90 papers, 2007 to 2025). "As mentioned, we have identified pathogenic variants in the PTPN11 gene that are causative for LEOPARD syndrome." (PMID 41516100, 2025). "In contrast, germline heterozygous mutations in PTPN11 that decreases its phosphatase activity are associated with 90% of the developmental disorder, Noonan Syndrome with Multiple Lentigines (NSML), earlier known as LEOPARD Syndrome22." (PMID 38965223, 2024). "Germline mutations in the PTPN11 gene cause NS, as well as other syndromes such as LEOPARD syndrome (LS), an uncommon congenital disorder characterized by multiple lentigines, cardiac involvement, facial dysmorphism, retardation of growth, and deafness." (PMID 39336782, 2024). "We examined LEOPARD syndrome (LS) in a patient with PTPN11 variants through pathological, electrophysiological, and anatomical studies." (PMID 39006213, 2024). "Another developmental disease caused by the SHP2 GOF mutation is LEOPARD syndrome, which results from heterozygous missense mutations in exons 7, 12, and 13 of the PTPN11 gene." (PMID 36768520, 2023). "Mutations in PTPN11 resulted in Noonan and LEOPARD syndromes, both of which manifested reproductive defects in the reproductive system such as male infertility." (PMID 36980830, 2023). "Another case was a known Leopard syndrome 1 causing variant, NM_002834: c.1530G > C p.(Gln510His), which was found in the PTPN11 gene." (PMID 37660152, 2023). "Three patients with syndromic SNHI, including one with Usher syndrome (MYO7A variants), one with LEOPARD syndrome (PTPN11 variant), and one with DiGeorge syndrome (TBX1 variant) exhibited unfavorable outcomes with CI." (PMID 36009393, 2022). "In humans, germline mutations of PTPN11 cause the developmental disorders Noonan and LEOPARD syndromes." (PMID 33755016, 2021). "Further genetic analysis showed the heteroziygous pathogenic variant c.1403 C>T in PTPN11 gene allowing Leopard Syndrome to be diagnosed." (PMID 32575496, 2020). "The Leopard Syndrome is an autosomal dominant genetic disease, mainly caused by PTPN11, instead of NF1, mutations." (PMID 32357851, 2020). "In fact, PTPN11 mutations cause the polymalformative Noonan and LEOPARD syndromes, two developmental disorders characterized by manifestations such as craniofacial abnormalities, growth defects, cardiac malformations, and—in some cases—mental retardation." (PMID 31708921, 2019). "The present study is the first and the only study on the human sample with PTPN11-mutated Leopard syndrome." (PMID 31722741, 2019). "Germline mutations in PTPN11 cause Noonan and LEOPARD syndromes, while somatic mutations in PTPN11 have been linked to childhood and adult malignancies." (PMID 27650545, 2016). "Ptpn11 gene mutations are common in patients with NS and LEOPARD syndrome (LS), two developmental disorders with pleiomorphic phenotypes." (PMID 26088100, 2015). "Evidence has confirmed that PTPN11 mutations are correlated with congenital heart defects in Noonan and LEOPARD syndromes." (PMID 25123136, 2014). "While the majority of reported patients with pathogenic variants in PTPN11 gene are associated with Noonan and multiple lentigines syndromes, which have gain-of-function as a mechanism of molecular pathogenesis, only 17 cases were linked MC to LoF variants in the PTPN11 gene." (PMID 40225915, 2024). "Interestingly, PTPN11 germ-line mutations are found in two syndromes of the RASopathy complex, Noonan and LEOPARD syndrome." (PMID 39120280, 2024).